LEPROTL1 (leptin receptor overlapping transcript like 1)
Description:
Negatively regulates growth hormone (GH) receptor cell surface expression in liver. May play a role in liver resistance to GH during periods of reduced nutrient availability.
Synonyms: My047; Vps55; HSPC112
Tractability: Antibody: UniProt predicts a signal peptide or a membrane-spanning region.
Gene: Protein-coding gene on chromosome 8 (30,095,408 to 30,177,208, forward strand). Ensembl gene ENSG00000104660.
Subcellular location: Membrane
Gene Ontology:
Molecular function: identical protein binding; protein binding
Biological process: late endosome to vacuole transport via multivesicular body sorting pathway; negative regulation of growth hormone receptor signaling pathway
Cellular component: endosome; membrane
Genetic constraint (gnomAD): Loss-of-function variants: 4 observed, 4.55 expected, observed/expected ratio (o/e) 0.88, 90% interval 0.43 to 1.76. That is too few expected variants to judge how well the gene tolerates losing a copy. Missense variants: 69 observed, 83.49 expected, observed/expected ratio (o/e) 0.83, 90% interval 0.68 to 1.01. Synonymous variants: 27 observed, 29.71 expected, observed/expected ratio (o/e) 0.91, 90% interval 0.67 to 1.25.
Homologues: Orthologues: pig LEPROTL1 (99% identical), guinea pig LEPROTL1 (98% identical), mouse Leprotl1 (98% identical), rat Leprotl1 (95% identical), tropical clawed frog leprotl1 (87% identical), zebrafish LEPROTL1 (82% identical), rabbit LEPROTL1 (82% identical), chimpanzee LEPROTL1 (76% identical), macaque LEPROTL1 (76% identical), Caenorhabditis elegans C30B5.2 (51% identical), Drosophila melanogaster CG30423 (40% identical). Paralogues in human: LEPROT (68% identical).
Diseases named in the same sentence as LEPROTL1 in open-access papers:
LEPROTL1 is named in the same sentence as 10 diseases in open-access papers, as found by Europe PMC text mining. Sharing a sentence is not in itself a finding about the gene and the disease. The quoted sentences say what the papers report.
bladder cancer (1 paper, 2023). "Mutations at specific hotspots in non-coding regions of ADGRG6, PLEKHS1, WDR74, TBC1D12 and LEPROTL1 frequently occur in bladder cancer (BC)." (PMID 36658180, 2023).
degenerative joint diseases (1 paper, 2014). "In contrast, LEPROTL1 was the only gene significantly underexpressed in the synovial membrane of CG as compared with both RA and OA, suggesting that this molecule may support inflammatory and/or degenerative joint diseases." (PMID 24690414, 2014).
hypertrophic cardiomyopathy (1 paper, 2022). A condition in which the myocardium is hypertrophied without an obvious cause. "Identical hypertrophic cardiomyopathy phenotypes were identified in Leprotl1 (encoding homozygous leptin receptor overlapping transcript-like 1) mutants compared to controls." (PMID 39195995, 2022). "For example, Fzd8- and Leprotl1-mutant mice had distinct TTE features of hypertrophic cardiomyopathy." (PMID 39195995, 2022).
lung carcinoma (1 paper, 2017). "Four homozygous deletions in lung cancer suggest a role for LEPROTL1 in keeping this feedback loop in check in normal lung cells." (PMID 29089486, 2017).
Obesity (1 paper, 2023). Accumulation of substantial excess body fat. "Elevated LEPROT was observed in patients with preoperative obesity (1.53 vs. 1.45, and p = 0.038), and LEPROTL1 was highly expressed in male patients with CP (1.38 vs. 1.20, and p = 0.031)." (PMID 37509115, 2023).
pancreatic cancer (1 paper, 2021). "The leptin receptor overlapping transcript-like 1 gene (LEPROTL1) encodes a membrane protein, and may play a role in liver resistance by suppressing the growth hormone activity, while the pancreatic cancer-related functions of LEPROTL1 remain unknown." (PMID 34926279, 2021). "We found that LEPROTL1 has increased expression in pancreatic cancer tissues compared to adjacent normal pancreatic tissues of the same patients." (PMID 34926279, 2021). "The bioinformatic analysis identified that LEPROTL1 was highly expressed in pancreatic cancer compared to matched normal pancreatic tissue of the same patients, suggesting a potential involvement in the etiopathology of PDAC." (PMID 34926279, 2021).
tumour (5 papers, 2017 to 2024). "The expression of leptin receptors, including LEPR (1.61 vs. 1.13, and p = 0.046), LEPROT (1.42 vs. 1.04, and p = 0.002), LEPROTL1 (1.31 vs.1.10, and p = 0.036), were elevated in CP tumor tissue compared to normal brain tissue." (PMID 37509115, 2023). "LEPROTL1 is listed in the COSMIC Cancer Gene Census as a tumour suppressor gene and is deleted in 5% of MIBCs; however, this does not appear to impact prognosis." (PMID 36658180, 2023). "Three genes (ZNF143, ALDOA and LEPROTL1) were among the top 30% of genes that are univariately informative of the proximity-to-tumour label." (PMID 29093438, 2017). "Two genes (ALDOA in module 5 and LEPROTL1 in module 2) also belonged to modules that significantly and positively correlated with proximity to tumour." (PMID 29093438, 2017). "We identified 42 and 16 TSGs monoallelically deleted in P2 and P5, respectively, including several TSGs deleted in both tumor samples (ARHGEF10, CDKN1B, ETNK1, ETV6, LEPROTL1, NRG1, PTPN6, and WRN) and many TSGs co-deleted in the same subclone as well as across multiple subclones." (PMID 38658552, 2024).
cancer (4 papers, 2021 to 2025). A tumor composed of atypical neoplastic, often pleomorphic cells that invade other tissues. "On the other hand, LEPROTL1 was characteristic of G2 cancer tissue samples and G1 cancer in whole blood." (PMID 34202922, 2021).
LEPROTL1 also shares sentences with these, for which no sentence is quoted: breast carcinoma (1 paper); migraine (1).